RNU7-104P (RNA, U7 small nuclear 104 pseudogene)
Gene: Small nuclear RNA gene on chromosome 2 (178,831,371 to 178,831,449, reverse strand). Ensembl gene ENSG00000238542.
Homologues: Orthologues: chimpanzee U7 (95% identical). Paralogues in human: RNU7-88P (66% identical), RNU7-48P (65% identical), RNU7-70P (65% identical), RNU7-37P (63% identical), RNU7-50P (63% identical), RNU7-92P (63% identical), RNU7-130P (62% identical), RNU7-144P (62% identical), RNU7-167P (62% identical), RNU7-174P (62% identical), RNU7-19P (62% identical), RNU7-24P (62% identical), and 141 more.